TIAM1 (TIAM Rac1 associated GEF 1)
Diseases named in the same sentence as TIAM1 in open-access papers (continued):
Sharing a sentence is not in itself a finding about the gene and the disease.
prostate carcinoma (6 papers, 2006 to 2021). A carcinoma that arises from epithelial cells of the prostate gland. "The extent of Tiam1 overexpression in prostate carcinoma was statistically significantly associated with the presence of LVI (P=0.031), GS ⩾7 (P=0.044) and with disease recurrence (P=0.016), but not with any other parameter." (PMID 17003780, 2006). "For example, high Tiam1 expression is an independent predictor of decreased disease-free survival for patients with prostate cancer." (PMID 24661909, 2014). "Of these, only preoperative PSA lost its prognostic impact in multivariate analysis, when combined with the extent of Tiam1 overexpression in prostate cancer." (PMID 17003780, 2006). "We found that Tiam1 is significantly overexpressed in almost all prostate carcinomas and HG-PIN lesions when compared to the corresponding benign secretory epithelium." (PMID 17003780, 2006). "Increased Tiam1 expression was observed in almost all prostate carcinomas when compared to the corresponding benign epithelial cells and the distribution of Tiam1 staining is reminiscent of that reported for alpha-methyl CoA racemase." (PMID 17003780, 2006). "This suggests that in prostate cancer strong Tiam1 overexpression is a new and independent predictor of tumour aggressiveness." (PMID 17003780, 2006). "In prostate cancer we found that strong Tiam1 overexpression (⩾3.5-fold) relative to the corresponding benign secretory epithelium is significantly associated with decreased DFS in univariate and most importantly also in multivariate analysis." (PMID 17003780, 2006). "In the present study, we show for the first time that in almost all prostate carcinomas the Tiam1 protein is significantly stronger expressed than in the corresponding benign prostate epithelial cells." (PMID 17003780, 2006). "On average, Tiam1 expression levels were 3.75-fold higher in prostate cancer and 3.6-fold higher in HG-PIN lesions, respectively, than in the corresponding benign secretory epithelial cells." (PMID 17003780, 2006). "The authors further demonstrated that Tiam1 overexpression in prostate cancer might be an independent prognostic marker of tumor recurrence." (PMID 27562113, 2016). "Therefore, our results suggest that strong Tiam1 overexpression is a new and independent predictor of disease recurrence for patients with prostate cancer and that tumours with strong Tiam1 overexpression require more aggressive treatment." (PMID 17003780, 2006). "In conclusion, the present study with up to 14.4-year follow-up shows that strong Tiam1 overexpression in prostate cancer relative to the corresponding benign prostate epithelial cells correlates with aggressive disease and is an independent prognostic indicator of disease recurrence." (PMID 17003780, 2006). "This suggests that similar as reported for alpha-methyl CoA racemase, strong Tiam1 expression could be used as an adjunct for the diagnosis of prostate cancer in difficult cases such as small foci in prostate needle biopsies." (PMID 17003780, 2006). "Similarly 58 out of 60 (96.7%) prostate carcinomas exhibited significantly stronger Tiam1 expression levels than the respective benign secretory epithelium (P<0.001)." (PMID 17003780, 2006). "Strong Tiam1 overexpression (i.e. ⩾3.5-fold) in prostate carcinomas relative to the respective benign prostatic epithelium was statistically significantly associated with disease recurrence (P=0.016), the presence of lymph vessel invasion (P=0.031) and high Gleason scores (GS) (i.e. ⩾7) (P=0.044)." (PMID 17003780, 2006). "Interestingly, significantly increased Tiam1 expression levels were not only observed in prostate cancer, but also in almost all preneoplastic HG-PIN lesions, indicating that increased Tiam1 expression occurs early in prostate carcinoma development." (PMID 17003780, 2006).
prostate carcinoma (continued). "Although the molecular mechanism, causing increased Tiam1 expression in HG-PIN lesions and prostate cancer, has yet to be determined, there are indications that it might result at least in part from increased Wnt/β-catenin signaling." (PMID 17003780, 2006). "Moreover, in multivariate analysis, the extent of Tiam1 overexpression relative to the corresponding benign epithelial cells proved to be an independent predictor of decreased disease-free survival (DFS) for patients with prostate cancer." (PMID 17003780, 2006). "In the present study, we have analysed Tiam1 expression in benign secretory epithelium, high-grade prostatic intraepithelium neoplasia (HG-PIN), and prostate carcinomas by semiquantitative immunohistochemistry." (PMID 17003780, 2006). "Moreover, Kaplan–Meier analysis showed that prostate cancer patients with pT3 stage and GS⩾7, respectively, could be further classified based on the extent of Tiam1 overexpression in their prostate cancer specimens to predict disease recurrence more accurately." (PMID 17003780, 2006). "By semiquantitative immunohistochemistry significant differences in Tiam1 expression became evident between benign prostatic glands on the one hand and HG-PIN lesions and prostate cancer on the other hand." (PMID 17003780, 2006). "Tiam1 proved significantly overexpressed in both HG-PIN (P<0.001) and prostate carcinomas (P<0.001) when compared to benign secretory epithelium." (PMID 17003780, 2006). "Together, our data suggest that strong Tiam1 overexpression relative to the corresponding benign epithelial cells is a new and independent predictor of decreased DFS for patients with prostate cancer." (PMID 17003780, 2006). "Silencing other PI3K-dependent Rac-GEFs expressed in prostate cancer cells, namely Tiam1, Vav2 or Vav3, also failed to reduce Rac1-GTP levels in PC3 cells." (PMID 32092966, 2020). "More specifically, the mean DFS time of patients with strong Tiam1 overexpression (⩾3.5-fold) in prostate carcinomas was 98 months (95% confidence interval (CI)=77–119), whereas the mean DFS time of patients with weak Tiam1 overexpression (<3.5-fold) was 136 months (95% CI=118–154)." (PMID 17003780, 2006). "In the present study, Tiam1 expression was analysed in benign secretory epithelium, pre-neoplastic high-grade prostatic intraepithelium neoplasia (HG-PIN) and prostate carcinomas of 60 R0-resected radical prostatectomy specimens by semiquantitative immunohistochemistry." (PMID 17003780, 2006).
renal cell carcinoma (6 papers, 2010 to 2019). "While, conversely, Tiam1 potentiates homotypic cell-cell adhesion and inhibits invasion in renal cell carcinoma cells." (PMID 24069171, 2013). "In human renal cell carcinoma cell lines, Tiam1 inhibits invasion through Rac-induced upregulation of tissue inhibitor of metalloproteinases-1 (TIMP-1) and TIMP-2." (PMID 24069171, 2013). "Consistently, expression of T-cell lymphoma invasion and metastasis-1 (Tiam1), a Rac-specific GEF, or constitutively active Rac1 in the renal cell carcinoma cell line ClearCa-28 inhibits cell migration, via enhancing E-cadherin-mediated adhesions." (PMID 27442895, 2017).
chronic lymphocytic leukemia (4 papers, 2018 to 2025). "Aberrant expression or mutations of Tiam1 has been shown to be associated with a variety of human cancer types including extranodal NK/T-cell lymphoma and chronic lymphocytic leukemia." (PMID 29416753, 2018). "Recently, it has been demonstrated that targeting Tiam1/Rac1 by using Tiam1 siRNA or inhibitors can reduce the chemoresistance in the proliferative and resistant pool of chronic lymphocytic leukemia (CLL) cells, which is considered to be associated with their recurrent relapses." (PMID 29416753, 2018). "In Th17 cells, Tiam1 binds the transcription factor RORγt and is required for the RORγt-dependent expression of interleukin IL-17a, and in chronic lymphocytic leukaemia cells, Tiam1 enables the expression of c-Myc." (PMID 38077328, 2023).
diabetic retinopathy (4 papers, 2015 to 2022). "Experimental models have shown that the inhibitors of its GEFs- Tiam1 and Vav2, inhibit the development of diabetic retinopathy via regulating Rac1-Nox2 signaling." (PMID 34063353, 2021). "We recently reported novel roles for Tiam1-Rac1-Nox2 axis in retinal mitochondrial dysfunction and cell death leading to the development of diabetic retinopathy." (PMID 25967961, 2015). "In summary, our current study suggest that hyperglycemic conditions promote activation of Tiam1-Rac1-Nox2 signaling module during early stages of diabetic retinopathy, which leads to activation of stress kinases such as the p38 MAP kinase." (PMID 25967961, 2015). "Tiam1-Rac1-mediated activation of Nox2 and p38 MAP kinase constitutes early signaling events leading to mitochondrial dysfunction and the development of diabetic retinopathy." (PMID 25967961, 2015). "Cross-talk between ceramides and Rac1 signaling via regulatory factors, including Tiam1 and Vav2, in the development of diabetic retinopathy, however, cannot be ruled out." (PMID 36202842, 2022).
liver cancer (4 papers, 2014 to 2024). An epithelial or non-epithelial malignant neoplasm that arises from the liver. "For example, SETDB1 can interact with Tiam1 to promote its expression, and further promote the progression of liver cancer." (PMID 38317200, 2024). "Evidence has been accumulating that Tiam1 plays a critical role in tumor initiation, promotion, and progression of various tumor cells including breast, colorectal, skin, and liver cancer." (PMID 29416753, 2018). "In conclusion, our study indicates that miR-141 inhibits liver cancer cells by negatively regulating the Tiam1 gene." (PMID 24551096, 2014).
lung adenocarcinoma (4 papers, 2014 to 2023). A carcinoma that arises from the lung and is characterized by the presence of malignant glandular epithelial cells. "The association of Tiam1 protein expression with the clinicopathological characteristics and the prognosis of lung adenocarcinoma were subsequently assessed." (PMID 24661909, 2014). "Higher Tiam1 expression is associated with lymph node metastasis, and is also an independent prognostic marker of poor survival in patients with lung adenocarcinoma." (PMID 24661909, 2014). "Moreover, we find that high nuclear TIAM1 is associated with advanced-stage lung adenocarcinoma and decreased survival." (PMID 37748077, 2023). "Importantly, high nuclear TIAM1 in clinical specimens is associated with advanced-stage lung adenocarcinoma, decreased patient survival, and inversely correlates with E-cadherin expression." (PMID 37748077, 2023). "There is some evidence that TIAM1 is overexpressed in lung adenocarcinoma (LUAD) tumors from patients; however, the subcellular localization of TIAM1 and its potential correlation with disease progression have not been evaluated." (PMID 37748077, 2023). "The overexpression of TIAM1 in lung adenocarcinoma is significantly related to advanced tumor grade and poor prognosis." (PMID 34526059, 2021). "Increased expression of Tiam1 protein was significant predictor of poor prognosis for patients with lung adenocarcinoma, especially for patients with stage I-II cancer." (PMID 24661909, 2014). "Our finding is in consistence with previous studies that Tiam1 expression was found in multiple different cancer tissues, confirms a significant relation between Tiam1 expression and genesis and development of lung adenocarcinoma." (PMID 24661909, 2014). "In summary, expression of Tiam1 protein was significantly higher in lung adenocarcinoma tissue than in normal tissue." (PMID 24661909, 2014). "In this study, we analyzed the expression of Tiam1 in 98 cases of lung adenocarcinoma tissues using immunohistochemistry." (PMID 24661909, 2014). "In this study, we attempted to investigate the expression of Tiam1 in lung adenocarcinoma using immunohistochemical staining and identify its relationship to lymph node metastasis, prognosis and clinicopathological features." (PMID 24661909, 2014). "In the current study, we are the first to report the prognostic value of Tiam1 expression for patients with lung adenocarcinoma." (PMID 24661909, 2014). "Partitioning defective protein 3 (Par3) can activate the Tiam1/Rac pathway to inhibit invasion and metastasis in many cancers; however, the role of Par3 in lung adenocarcinoma remains unknown." (PMID 27588399, 2016). "Nevertheless, whether these finding of Tiam1 can be extended to lung adenocarcinoma remains elusive." (PMID 24661909, 2014). "Immunohistochemical analysis showed that 60 of 98 (61.22%) adenocarcinoma tissues showed high expression of Tiam1, and high Tiam1 expression was significantly associated with advanced TNM stage (P < 0.0005) and lymph node status (P < 0.0005) of lung adenocarcinoma." (PMID 24661909, 2014). "A future study will investigate whether Tiam1 can serve as a novel therapeutic target in lung adenocarcinoma." (PMID 24661909, 2014). "Moreover, the lung adenocarcinoma patients with low Tiam1 expression had higher overall survival than patients with high Tiam1 expression (log rank value = 10.805, P = 0.001)." (PMID 24661909, 2014). "Our analysis further showed that Tiam1 overexpression correlates with lymph node metastasis of patients with lung adenocarcinoma, which suggests that Tiam1 might play an important role in the progression and invasion of lung adenocarcinoma." (PMID 24661909, 2014). "Furthermore, multivariate analysis indicated that high expression of Tiam1 protein was an independent prognostic factor for overall survival (P = 0.011) in patients with lung adenocarcinoma." (PMID 24661909, 2014).
lung adenocarcinoma (continued). "Therefore, we can conclude that Tiam1 serves as a biomarker for predicting prognosis of lung adenocarcinoma patients." (PMID 24661909, 2014). "Since Tiam1 overexpression can be a new predictor of poor prognosis of patients in a variety of tumors, it may be served as a new and independent predictor of prognosis for patients with lung adenocarcinoma as well." (PMID 24661909, 2014). "However, further studies are needed to verify our current findings, and we will investigate whether Tiam1 is a useful therapeutic target in lung adenocarcinoma." (PMID 24661909, 2014). "Tiam1 may serve as a useful molecular marker for lung adenocarcinoma progression and invasion." (PMID 24661909, 2014). "Tiam1 protein expression level was determined by immunohistochemistry in 98 lung adenocarcinoma tissues and 30 non-neoplastic tissues (used as a normal control)." (PMID 24661909, 2014). "However, the potential prognostic relevance of Tiam1 expression in lung adenocarcinoma has no been investigated." (PMID 24661909, 2014).
lymph node metastasis (4 papers, 2014 to 2023). "We found that Tiam1 expression increased in PC tissues and was associated with lymph node metastasis." (PMID 38017477, 2023). "High Tiam1 expression was significantly associated with relapse (P < 0.001), lymph node metastasis (P = 0.003), and stage III/IV cancers (P < 0.001)." (PMID 26369827, 2015). "Of the 194 evaluable patients, those with advanced disease, lymph node metastasis at diagnosis, and recurrence or metastasis during follow-up had a higher tendency of having high Tiam1 expression as compared with their counterparts (P < 0.05)." (PMID 26369827, 2015). "High Tiam1 expression was also associated with higher relapse rates, higher mortality, lymph node metastasis, and stage III/IV cancers as compared with low Tiam1 expression (all P < 0.05)." (PMID 26369827, 2015). "However, our contingency table analysis showed that Tiam1 expression did not correlate with lymph node metastasis, but associated with Ki-67 expression." (PMID 27562113, 2016).
renal carcinoma (4 papers, 2010 to 2020). A carcinoma arising from the epithelium of the renal parenchyma or the renal pelvis. "Some of these genes belong to pathways known to be dysregulated in renal cancer (e.g., ITGAV, TIAM1, and PIK3CB)." (PMID 30942869, 2019).
T-cell lymphoma (4 papers, 2012 to 2020). "The hub gene in the brown module co-expression network was TIAM1 (T Cell Lymphoma Invasion and Metastasis 1)." (PMID 32493431, 2020). "Tiam1 expression was observed to be higher in extranodal NK/T-cell lymphoma tissue than the control." (PMID 29416753, 2018). "rs2660852 flanked 5′UTR of LTA4H (leukotriene A4 hydrolase), rs477145 was intronic to TIAM1 (T-cell lymphoma invasion and metastases) and rs2835931 was intronic to KCNJ6 (potassium channel, inwardly rectifying subfamily J, member 6)." (PMID 26959888, 2016). "The proximal protein coding genes included LTA4H (leukotriene A4 hydrolase) on chromosome 12, TIAM1 (T-cell lymphoma invasion and metastases) and KCNJ6 (potassium channel, inwardly rectifying subfamily J, member 6) both on chromosome 21." (PMID 26959888, 2016). "Following the UCSC UMD3 assembly, candidate genes could be identified at or close to the peaks for regions #2 (TIAM1: T-cell Lymphoma Invasion and Metastasis 1), # 3 (GRIK1: Glutamate Receptor, Ionotropic, Kainate 1) and #4 (RAI14: Retinoic Acid Induced 14)." (PMID 22675421, 2012).
Autoimmunity (3 papers, 2016 to 2024). The occurrence of an immune reaction against the organism's own cells or tissues. "Moreover, RAC1, along with TIAM1, is implicated in interleukin 17A (IL-17A) transcription and has a role in autoimmunity." (PMID 38577601, 2024). "Here, the authors show that nuclear Tiam1 and Rac1 bind to RORγt on the IL-17 promoter, activating its transcription, and that inhibiting Tiam1/Rac1 is beneficial in a mouse model of autoimmunity." (PMID 27725632, 2016). "Here, we show the guanine nucleotide exchange factor, Tiam1, and its cognate Rho-family G protein, Rac1, regulate interleukin (IL)17A transcription and autoimmunity." (PMID 27725632, 2016).
colon adenoma (3 papers, 2008 to 2020). An adenoma that arises from the colon. "Recent studies showed that TIAM1 gene was overexpressed in human colonic adenomas, acting as an oncogene, which abnormal promoter methylation of TIAM1 promoter was tightly associated with aberrant expression in CRC." (PMID 32517740, 2020).
esophageal squamous cell carcinoma (3 papers, 2013 to 2025). Esophageal squamous cell carcinoma (ESCC) is a type of esophageal carcinoma (EC) that can affect any part of the esophagus, but is usually located in the upper or middle third. "Past studies have found that sorafenib triggers antiproliferative and pro-apoptotic signals in human esophageal adenocarcinoma cells, and Tiam1 siRNA can enhance the sensitivity of sorafenib on esophageal squamous cell carcinoma in vivo." (PMID 40855044, 2025).
glioma (3 papers, 2010 to 2023). A benign or malignant brain and spinal cord tumor that arises from glial cells (astrocytes, oligodendrocytes, ependymal cells). "Current studies on the role of POLA1 or TIAM1 in glioma cells or mesenchymal stem cells are limited; thus, further studies should focus on these issues." (PMID 37005685, 2023). "Among these, CDH13, TIAM1 and PCDH17 were up- and FLRT1 and OPCML down-regulated, thus indicating that the invasion capacity of glioma cells can be altered by cisplatin treatment." (PMID 21637621, 2010). "Our results show that the effects of 1A-116, a drug designed to specifically inhibit the Rac1 signaling pathway by preventing its interaction with TIAM1, were also modulated by the circadian clock in LN229 cells in vitro and showed a time-of-day dependence in a glioma tumor model in vivo." (PMID 34371781, 2021). "The results obtained for both mRNA and protein levels indicate that TIAM1 is modulated by a functional circadian clock in LN229 glioma cells, while Rac1 showed a non-circadian expression at the mRNA level." (PMID 34371781, 2021).